PRR3 (proline rich 3)
Synonyms: CAT56; Em:AB014077.1; Em:AB023052.2
Tractability: PROTAC: its protein half-life has been measured.
Gene: Protein-coding gene on chromosome 6 (30,557,274 to 30,563,723, forward strand). Ensembl gene ENSG00000204576.
Subcellular location (Human Protein Atlas): Nucleoplasm; Cytosol
Gene Ontology:
Molecular function: protein binding; RNA binding; enzyme-substrate adaptor activity; protein phosphatase inhibitor activity; metal ion binding
Biological process: positive regulation of termination of RNA polymerase II transcription, poly(A)-coupled
Cellular component: chromatin; PTW/PP1 phosphatase complex
Genetic constraint (gnomAD): Loss-of-function variants: 13 observed, 21.42 expected, observed/expected ratio (o/e) 0.61, 90% interval 0.39 to 0.96. The upper end of that interval is the gene's LOEUF score, 0.96, which puts it in group 4 of 6, group 1 being the genes least tolerant of losing a copy. Missense variants: 209 observed, 238.14 expected, observed/expected ratio (o/e) 0.88, 90% interval 0.78 to 0.98. Synonymous variants: 84 observed, 85.82 expected, observed/expected ratio (o/e) 0.98, 90% interval 0.82 to 1.17.
Homologues: Orthologues: chimpanzee PRR3 (99% identical), macaque PRR3 (98% identical), dog PRR3 (90% identical), rabbit PRR3 (89% identical), mouse Prr3 (83% identical), guinea pig PRR3 (61% identical). Paralogues in human: PPP1R10 (43% identical), ZC3H18 (29% identical).
Diseases named in the same sentence as PRR3 in open-access papers:
PRR3 is named in the same sentence as 2 diseases in open-access papers, as found by Europe PMC text mining. Sharing a sentence is not in itself a finding about the gene and the disease. The quoted sentences say what the papers report.
infection (1 paper, 2016). The state of being infected such as from the introduction of a foreign agent such as serum, vaccine, antigenic substance or organism. "A transcript encoding PRR3 was up-regulated by infection with CTV-B6 and CaLas-B232." (PMID 27169471, 2016).
PRR3 also shares sentences with these, for which no sentence is quoted: tumor (1 paper).